PLEK2 (pleckstrin 2)
Diseases named in the same sentence as PLEK2 in open-access papers (continued):
Sharing a sentence is not in itself a finding about the gene and the disease.
tumor (continued). "While our findings supported PLEK2’s role in tumor progression and immune modulation, further studies focusing on specific molecular mechanisms, such as the downstream effects of PLEK2 on AKT pathway or its influence on macrophage polarization, would help solidify these causative links." (PMID 39546161, 2024). "Recently, several studies have noted the importance of PLEK2 in tumor invasion and metastasis." (PMID 34331382, 2021). "Recently, several studies have noted the importance of PLEK2 in tumor metastasis." (PMID 34331382, 2021). "In addition, there was a difference in the size and weight of the tumours over time in the PLEK2 upregulation and downregulation groups." (PMID 34394345, 2021). "Here, PLEK2 was first shown to have differential expression in tumour tissue and normal oesophageal squamous epithelial tissue, which could be related to the finding that PLEK2 expression predicts a poor prognosis in ESCC." (PMID 34601488, 2021). "In the immune environment of ESCC, CAFs are a major source of TGF-β, which may be the main reason that PLEK2 is highly expressed in ESCC tumours." (PMID 34601488, 2021). "PLEK2 is little known before and its relation with tumor metastasis is poorly understood." (PMID 31182136, 2019). "As EMT process plays indispensable role in tumor metastasis, we investigated whether the function of PLEK2 in cell spreading promoted EMT process." (PMID 31182136, 2019). "Considering the significance of programmed death-ligand 1 (PD-L1), tumor mutation burden (TMB), and microsatellite instability (MSI) as important biomarkers for immunotherapy response, we assessed the correlation between PLEK2 expression and TMB/MSI across multiple cancer types." (PMID 39546161, 2024). "Functional validation confirmed that PLEK2 was overexpressed in LUAD tissues and promoted tumor cell proliferation, migration, and colony formation." (PMID 40552290, 2025). "We analyzed PLEK2 expression in tumor tissues using the TIMER database, which showed elevated PLEK2 levels across various tumor types compared to control tissues." (PMID 39687904, 2024). "Reducing Plek2 expression seemed to restore this balance, allowing for greater CD8 T cell infiltration and enhancing the anti-tumor effects of PD-1 blockade." (PMID 39546161, 2024). "To assess this potential, we calculated Tumor Immune Dysfunction and Exclusion (TIDE) scores—a well-established biomarker for predicting immunotherapy outcomes—for patients stratified by PLEK2 expression levels." (PMID 39546161, 2024). "The expression of PLEK2 in different tumor types was analyzed using the online tool TIMER, which demonstrated that PLEK2 expression was generally elevated in a wide range of tumors." (PMID 39687904, 2024). "The expression levels of GAPDH, FSCN1, SLC2A1, FAM83A, PLEK2, and GJB3 all presented significant differences between tumor tissues and normal tissues." (PMID 38370379, 2024). "This analysis revealed significantly elevated PLEK2 expression in most cancers, except for ACC, SKCM, TGCT, DLBC, LIHC, and PCPG (normal vs. tumor, P < 0.05, Student’s t-test)." (PMID 39546161, 2024). "NAT10, CCT3, PLEK2, HOXB7, FOXD1, SEC61G, and so on have been identified as tumor markers in HNSCC by performing TCGA HNSCC database analysis." (PMID 37679666, 2023). "The detection of PLEK2 expression in paired fresh tumour tissues and adjacent normal tissues from four ESCC patients who underwent surgery showed that PLEK2 expression was higher in tumour tissues than in paired adjacent nontumour tissues." (PMID 34601488, 2021). "Stable PLEK2-overexpressing MGC803 cells showed remarkably improved tumour growth and tumour weight compared with those observed in the control groups." (PMID 34394345, 2021). "In addition, we investigated whether PLEK2 could promote GBC tumor metastasis in xenograft models." (PMID 31182136, 2019).
tumor (continued). "Further research was necessary to dissect these mechanisms and understand how PLEK2’s effects on TMB and the tumor microenvironment (TME) could be leveraged to improve immunotherapy outcomes." (PMID 39546161, 2024). "In addition, we assessed the expression of molecules such as ANKRD22, GINS3, POLE2, PLEK2, FERMT1 and METTL14 in subcutaneous tumours and lung metastatic tissues." (PMID 39021049, 2024). "In contrast, in the Plek2 overexpression group that received PD-1 treatment, tumor growth rates and weights increased, though not statistically significantly." (PMID 39546161, 2024). "Additionally, we examined PLEK2 protein level in 14 pairs of GBC and non-tumor tissues using western blot analysis which showed most GBC tissues had higher PLEK2 protein level than the normal control." (PMID 31182136, 2019). "However, the biological functions of PLEK2 in tumour progression have not been well defined, especially in gastric tumourigenesis." (PMID 34394345, 2021).
cancer (21 papers, 2011 to 2025). A tumor composed of atypical neoplastic, often pleomorphic cells that invade other tissues. "Recent studies demonstrated that PLEK2 is highly expressed and associated with worse prognosis and overall survival in various cancers." (PMID 40682666, 2025). "Our comprehensive analysis revealed that PLEK2 expression was significantly associated with various immune regulatory genes across multiple cancer types, including CD276 (B7-H3), CD274 (PD-L1), and FAS." (PMID 39546161, 2024). "To assess the prognostic value of PLEK2 across various cancers, we performed survival association analyses including overall survival (OS), progression-free survival (PFS), disease-specific survival (DSS), and disease-free survival (DFS)." (PMID 39546161, 2024). "PLEK2 expression was positively associated with the infiltration of cancer-associated fibroblasts (CAFs), CD4 T cells, macrophages, and natural killer (NK) cells, but negatively associated with CD8 T cells and B cells." (PMID 39546161, 2024). "The analyses of OS, PFS, DSS, and DFS revealed that PLEK2's expression was significantly linked to the prognosis of cancer patients." (PMID 39546161, 2024). "To further understand the underlying biological function of PLEK2 in cancer development, we searched the functional states of PLEK2 using cancerSEA and found PLEK2 was correlated with metastasis and hypoxia in HNSCC." (PMID 34331382, 2021). "Further researches are needed to elucidate the mechanism underlying the role that PLEK2 plays in EMT regulation during cancer progression." (PMID 34394345, 2021). "These associations indicated that PLEK2 could serve as a more precise biomarker in these cancers, aiding in the stratification of patients who might benefit from targeted therapies." (PMID 39546161, 2024). "Given the intricate relationships observed, future research endeavors should aim at unraveling these complex functions and delving into the underlying mechanisms by which PLEK2 influences cancer prognosis, thus paving the way for targeted therapeutic strategies and precision medicine." (PMID 39546161, 2024). "Notably, high PLEK2 expression is associated with poor prognosis in several cancers, although its impact varies across different cancer types." (PMID 39546161, 2024). "Herein, our studies suggest that PLEK2 is an attractive target for the treatment of cancers via the regulation of TYMS expression." (PMID 40682666, 2025). "To explore the potential role of PLEK2 in cancers, we analyzed the mRNA levels of PLEK2 with the published next-generation sequencing data from Oncomine comprising major types of human cancer with respective normal tissues." (PMID 40682666, 2025). "We then evaluated the prognostic significance of PLEK2 across human cancers using univariate Cox regression." (PMID 40552290, 2025). "While PLEK2 has been implicated in EMT and metastasis in several cancers, its role in LUAD has been less explored." (PMID 40552290, 2025). "Given that PLEK2 is required for CCSCs, targeting PLEK2 inhibition has the potential to eliminate CCSCs via the reduction of self-renewal accompanied by its differentiation into cancer cells." (PMID 40682666, 2025). "These pathways were negatively enriched in patients with high PLEK2 expression in several cancers, including BRCA, COAD, LUSC, PRAD, SKCM, THCA, and UCEC." (PMID 39546161, 2024). "Functional assays showed that PLEK2 knockdown inhibited proliferation and migration in human cancer cell lines." (PMID 39546161, 2024). "Knockdown of PLEK2 in multiple human cancer cell lines led to decreased proliferation and migration." (PMID 39546161, 2024). "Survival analysis demonstrated that elevated PLEK2 expression correlated with poor prognosis in specific cancers, though its impact varied across cancer types." (PMID 39546161, 2024). "This study systematically examined the expression patterns, prognostic relevance, and functional impact of PLEK2 across multiple cancer types." (PMID 39546161, 2024).
cancer (continued). "In conclusion, PLEK2 played a multifaceted role in cancer progression and immune response modulation." (PMID 39546161, 2024). "In conclusion, our comprehensive pan-cancer analysis demonstrated that PLEK2 played a multifaceted role in cancer progression and immune modulation." (PMID 39546161, 2024). "Building on our single-cell analysis indicating that PLEK2 is expressed in various immune cells, particularly macrophages, we aimed to investigate the predictive role of PLEK2 expression in cancer immunotherapy responses across multiple cancer types." (PMID 39546161, 2024). "For instance, PLEK2 has been reported to promote cancer stemness, tumorigenesis, invasion, and metastasis." (PMID 38970307, 2024). "Dysregulated methylation of WT1, PLEK2, MRAS, and RXRA in the twin with B‐ALL increases cancer susceptibility." (PMID 38970307, 2024). "To investigate PLEK2 expression patterns across various cancers, we first examined its basal expression in normal human tissues using the GTEx database." (PMID 39546161, 2024). "In this study, we performed an extensive analysis of PLEK2 across various cancers using publicly available datasets, including The Cancer Genome Atlas (TCGA) and Gene Expression Omnibus (GEO)." (PMID 39546161, 2024). "PLEK2 mRNA is notably elevated in multiple organs prone to cancer development, while lower expression levels are observed in non-proliferative tissues like the heart and brain." (PMID 39546161, 2024). "We also found that PLEK2 expression correlates with immunosuppressive states within tumors and has the potential to predict immunotherapy efficacy in certain cancers." (PMID 39546161, 2024). "Consistent with our findings in nine human cancer cell lines, Plek2 knockdown significantly inhibited both proliferation and migration of LLC cells, while Plek2 overexpression enhanced these abilities." (PMID 39546161, 2024). "We then compared PLEK2 mRNA levels between cancerous and normal tissues, compiling data from 30 cancer types in the TCGA and GTEx databases." (PMID 39546161, 2024). "Our analyses revealed that PLEK2 is overexpressed in multiple cancer types at both the mRNA and protein levels." (PMID 39546161, 2024). "The JAK2/STAT5 pathway is commonly activated in hematologic malignancies, suggesting a broader application of Plek2 inhibitors in cancers." (PMID 36719747, 2023). "Future clinical studies using Plek2 inhibitors in various Akt-activated cancers would be informative." (PMID 36719747, 2023). "In the dataset of Peng Head‐Neck, PLEK2 was upregulated in cancers of the oral cavity with a FC of 3.833." (PMID 34331382, 2021). "The CCLE database revealed that the highest level of PLEK2 expression in diverse cancers was observed in cell lines of the pancreas, followed by cell lines of the upper aerodigestive tract including head and neck sites, such as mouth, pharynx, larynx." (PMID 34331382, 2021). "Real-time PCR analysis showed that PLEK2 mRNA expression was increased in 19 of 20 (95%) cases of cancer tissues." (PMID 34394345, 2021). "Increasing evidences suggest that PLEK2 plays a cancer-promoting role in tumorigenesis and metastasis." (PMID 34869363, 2021). "Several lines of evidences suggest that PLEK2 is a potential therapeutic target for the treatment of cancers." (PMID 34869363, 2021). "Regarding phenotype comparisons for which these genes were representative, both GCSH and PLEK2 distinguished cancer grades: GCSH expression was lower in G4 than in G3, while PLEK2 was higher in G4 compared to G2." (PMID 34204789, 2021). "In our study, we first confirmed the high expression of PLEK2 in a variety of cancer tissues and cancer cell lines, including HNSCC." (PMID 34331382, 2021). "We next performed the drug sensitivity analysis among PLEK2 and its hub genes in Genomics of Drug Sensitivity in Cancer (GDSC)." (PMID 34331382, 2021). "However, despite these insights, there remains a notable gap in the systematic exploration of PLEK2’s role across different cancer types." (PMID 39546161, 2024).
cancer (continued). "Increasing evidence suggests that PLEK2 plays a role in the progression of various cancers." (PMID 39546161, 2024). "Using data from The Cancer Genome Atlas (TCGA), Genotype Tissue Expression Project (GTEx), and the Human Protein Atlas, we analyzed PLEK2 expression in both cancerous and normal tissues, revealing significant overexpression of PLEK2 in various cancers at the mRNA and protein levels." (PMID 39546161, 2024). "Furthermore, cell migration assays revealed that PLEK2 knockdown markedly inhibited the migration of all nine cancer cell lines." (PMID 39546161, 2024). "In this study, we comprehensively investigated the role of PLEK2 through a pan-cancer analysis." (PMID 39546161, 2024). "Our analysis revealed that elevated PLEK2 expression was significantly associated with increased expression of several key immune checkpoint molecules, such as CD276 (B7-H3), CD274 (PD-L1), LGALS9, PVR (CD155), and FAS across a wide spectrum of cancers." (PMID 39546161, 2024). "Overall, these findings suggested that PLEK2 was overexpressed in various cancers and might play a significant role in tumorigenesis, highlighting its potential as a clinical diagnostic marker." (PMID 39546161, 2024). "Based on our pan-cancer single-cell analysis, we hypothesized that Plek2 may also affect macrophage infiltration within tumors." (PMID 39546161, 2024). "Thus, the small-molecule Plek2 inhibitors have important implications for treating MPNs and possibly other cancers with activated Akt signaling." (PMID 36719747, 2023). "Recently, PLEK2 was found to play crucial roles in cancer metastasis and progression." (PMID 31182136, 2019). "Notably, PLEK2 is highly expressed in multiple types of cancer including CRC." (PMID 40682666, 2025). "To investigate whether PLEK2 expression influences immune cell infiltration in human cancers, we performed Estimating the Proportions of Immune and Cancer cells (EPIC) analysis to compare immune scores between patients with high and low PLEK2 expression across 34 cancer types." (PMID 39546161, 2024). "Given that PLEK2 exerts strong regulatory effects on actin cytoskeletal actin rearrangement and subsequent formation of large lamellipodia and the peripheral ruffle of cells, PLEK2 upregulation may directly lead to enhanced invasive capability of cancer cells." (PMID 34869363, 2021). "Therefore, the development of small molecules that modulate the function of PLEK2 is not only beneficial for the treatment of diverse cancers, but also provides extremely useful tools for studying PLEK2 functions as a powerful complementary method to the genetic methods." (PMID 34869363, 2021). "Analysis of the Genomics of Drug Sensitivity in Cancer (GDSC) dataset identified Navitoclax, Methotrexate, and YM201636 as the top compounds showing a positive correlation with PLEK2 expression." (PMID 39546161, 2024). "These genes are GAPDH, FSCN1, SLC2A1, FAM83A, PLEK2, and GJB3, some of which have been previously documented in various cancer types." (PMID 38370379, 2024). "A comprehensive pan-cancer analysis is lacking, particularly one that investigates the prognostic significance of PLEK2 and its potential to predict responses to immunotherapy." (PMID 39546161, 2024). "PADI4 inhibitor treatment in cancer cells downregulated four genes related to metastatic cancer phenotypes: Laminin Subunit Gamma 2 (LAMC2), C-X-C Motif Chemokine Ligand 8 (CXCL8), Niban Apoptosis Regulator 1 (FAM129A), and Pleckstrin 2 (PLEK2)." (PMID 36233212, 2022). "Further analysis using blood fractionation showed that CD45− and CD45+ populations were responsible for the altered expression levels of PLEK2 and C1QB, respectively, indicating the importance of analyzing whole blood cells for blood-based biomarker studies of cancer." (PMID 21698244, 2011). "The genes (PLEK2 and C1QB) identified in this study have not been well investigated in cancer biology." (PMID 21698244, 2011).
infection (1 paper, 2012). The state of being infected such as from the introduction of a foreign agent such as serum, vaccine, antigenic substance or organism. "Then we evaluated virulent F. tularensis SchuS4 infection of THP-1 cells in which six top hit genes (TNFRSF9, SERPINI1, HLA-DBR1, PLEK2, ATG5 and ATG16L1) were knocked down by individual lentiviral shRNA." (PMID 22359626, 2012).
PLEK2 also shares sentences with these, for which no sentence is quoted: acute myeloid leukemia (1 paper); asthma (1); biliary tract cancer (1); bladder cancer (1); bladder urothelial carcinoma (1); breast invasive carcinoma (1); carcinoid tumor (1); cervical squamous cell carcinoma (1); colon adenocarcinoma (1); diabetes (1); endocervical adenocarcinoma (1); head and neck cancer (1); hematologic malignancies (1); kidney Chromophobe (1); Listeria monocytogenes infection (1); lung squamous cell carcinoma (1); malignant neoplasms of the digestive system (1); neurofibromatosis (1); nicotine addiction (1); osteosarcoma (1); ovarian carcinoma (1); pleural mesothelioma (1); primary myelofibrosis (1); rectum adenocarcinoma (1); renal adenocarcinoma (1); renal carcinoma (1); Splenomegaly (1); uterine corpus endometrial carcinoma (1); uveal melanoma (1).